LGR5 (leucine rich repeat containing G protein-coupled receptor 5)
Diseases named in the same sentence as LGR5 in open-access papers (continued):
Sharing a sentence is not in itself a finding about the gene and the disease.
tumor (continued). "In vivo, repression of PCs activity by the general PC inhibitors α1-PDX, Spn4A, or decanoyl-RVKR-chloromethylketone (CMK) significantly reduced tumor expression levels of the stem cell markers LGR5 and NANOG that are associated with reduced tumor xenografts." (PMID 35267511, 2022). "Transplantation of engineered tumorigenic CRC organoids into mice and subsequent YAP activation led to loss of Lgr5+ cells and tumor regression." (PMID 36358834, 2022). "In GC patients, the high LGR5 expression in tumor tissue is associated with adverse clinicopathological features and a dismal prognosis." (PMID 35326607, 2022). "IL-25 promotes tumorigenesis through maintaining tumour stemness, and genetic IL-25-deficiency led to reduced expression of stem cell markers Lgr5, CD133 and DCLK1." (PMID 36263033, 2022). "While the expression of most B-cell-related genes is associated with better survival in both PFS and OS, there are some tumor-related genes in which the expression is associated with a decrease in survival, such as LGR5 or KCNA1." (PMID 36012390, 2022). "LGR5 overexpression has been associated with cancer recurrence and tumor formation in breast cancer cells through WNT/β-catenin signaling activation." (PMID 34946546, 2021). "When they specifically targeted Lgr5−/Krt19+ cells with an inducible APC homozygous mutation, these cells initiated autochthonous malignant tumors containing mutated Lgr5+ cells—therefore generated through cell dedifferentiation—that drove tumor development." (PMID 33671641, 2021). "The authors demonstrated that phosphatase and tensin homolog (Pten), a natural inhibitor of Akt pathway, loss is unnecessary for tumor formation in Lgr5 + ISCs." (PMID 33827616, 2021). "Recently, a self-maintaining pericentral group of LGR5+ hepatocytes was shown to be highly susceptible to hepatocarcinogenesis, and was determined to be primarily responsible for tumor development in diethylnitrosamin (DEN)-induced HCC." (PMID 32183251, 2020). "The data imply that upregulation of Rspo‐Lgr5 signalling upon Nedd4/Nedd4l loss increases tumour predisposition and progression in Apcmin animals by promoting Wnt activation and ISC self‐renewal." (PMID 31867777, 2020). "The authors showed that DT treatment inhibited tumor growth concomitant with loss of the EGFP+/LGR5+ cells." (PMID 32183251, 2020). "Increasing evidence have indicated that endogenous Lgr5+ cell population is implicated in tumor initiation, progression, and metastasis." (PMID 31358061, 2019). "Analyses according to Spearman-Rho revealed after Bonferroni correction a significant correlation between LGR5 transcript variants mRNA expression and the mRNA expression of tumor-associated markers." (PMID 30770730, 2019). "These cells filled the niche vacated by the LGR5+ cells and began to re-express LGR5, causing initial decreases in tumour volume but eventual tumour reconstitution following cessation of treatment." (PMID 30792270, 2019). "Studies have shown that Lgr5 is implicated in tumor growth and metastasis via various signaling pathways." (PMID 31358061, 2019). "An association between an elevated LGR5 expression and unfavourable outcome has been reported for several tumor entities." (PMID 30770730, 2019). "Several studies have already shown an association between LGR5 expression in GC and increased tumor progression, metastasis, and worse prognosis." (PMID 31827644, 2019). "Meanwhile, LGR5 expression has repeatedly been demonstrated to be associated with the tumor grade of differentiation, with differing orders." (PMID 30501144, 2019). "Nevertheless, both groups confirm a distinctive association between tumoral expression of LGR5 and tumor stage." (PMID 30501144, 2019). "Taken together, our study has shown that the high expression of Lgr5 and high number of tumor-infiltrating Tregs are both associated with poor OS in patients with GC." (PMID 31417548, 2019).
tumor (continued). "Collectively, univariate and multivariate analysis results indicate that high Lgr5 expression in association with a high number of tumor-infiltrating Tregs promotes cancer progression and poor prognosis in GC." (PMID 31417548, 2019). "Aberrant expression of LGR5 was significantly associated with patient age (P = 0.006), tumor histologic type (P < 0.001), and distant metastasis (P = 0.025)." (PMID 29777575, 2018). "During 18 weeks, LGR5+ SiHa-LGR5 cells also caused a lower tumor-free rate (12.5% for LGR5+ SiHa-LGR5 cells versus 50% for LGR5– SiHa-AcGFP cells) than LGR5– SiHa-AcGFP cells (P<0.01)." (PMID 28880275, 2017). "Overexpression of LGR5 in human PTC is associated with several markers of tumor aggressiveness and predicted LN metastasis." (PMID 29383135, 2017). "Within intestinal epithelium, loss of Apc in the LGR5+ve stem cell compartment leads to adenoma, whereas tumours rarely form from differentiated cells." (PMID 27558455, 2016). "In LGR5-positive tumors associated with metastatic lymph nodes, tumor foci in lymph nodes were similarly LGR5 positive." (PMID 26416247, 2015). "We test the association of LGR5 tumor expression with markers of PTC aggressiveness using a Discovery Cohort (n = 26 patients) and a Validation Cohort (n = 157 patients)." (PMID 26416247, 2015). "Clinicopathological analysis unraveled the reverse association of positive lgr5 methylation with higher tumor grade and invasiveness, in agreement with the notion that over-expression of lgr5 was associated with the more malignant and invasive cancers." (PMID 26599100, 2015). "We conclude that overexpression of LGR5 is associated with markers of tumor aggressiveness in human PTC." (PMID 26416247, 2015). "In three separate PTC human cohorts treated at Duke from 2005–2013, we demonstrated that LGR5 positivity was highly associated with markers of tumor aggressiveness." (PMID 26416247, 2015). "Intriguingly, both these studies each include an individual relapsed tumour with missense mutations of LGR5, ie 2 mutations in a total of 39 relapsed tumours analysed (5%)." (PMID 26517508, 2015). "In other tissue types, constitutively active Wnt signaling increases proliferation of Lgr5-positive populations and can cause tumor formation." (PMID 25493560, 2014). "Significantly, research has demonstrated that LGR5 plays a role in tumor progression likely due to mutational activation of the Wnt pathway." (PMID 24172981, 2014). "Accumulated studies have shown that LGR5 is closely associated with tumorigenesis and tumor invasion in CRC and is likely to be a relevant marker of CSCs in CRC." (PMID 25192390, 2014). "Based on these findings, we postulated that IM in the stomach enhances the risk of tumor development by increasing the Lgr5+ cell population, which is highly susceptible to transformation by APC mutation." (PMID 24340024, 2013). "Somatic cancer mutations of LGR5 have also been identified, all of which are distinct missense mutations with the exception of one truncation, supporting its role as a tumor suppressor." (PMID 22615920, 2012). "Colon tumorigenesis offers a unique opportunity to study cell state, adult stem cells, and tumorigenesis given the hierarchical organization of stem and progenitors within the crypts along with evidence implicating mutated LGR5+ colon stem cells as a tumor initiating cell." (PMID 39895630, 2025). "Organoids were isolated from mice containing a variety of different combinations of gene mutations ApcLoxP, LSL-KrasG12D, Tgfβr2LoxP, and p53LoxP under an inducible Lgr5 promoter to determine if metastatic tumours could be generated by gene mutations." (PMID 41463180, 2025). "Loss of FXR led to formation of a tumor-promoting microenvironment, with enrichment of pro-tumorigenic signaling pathways, less protective epithelial mucus production, and increased numbers of Lgr5 progenitor cells." (PMID 40139565, 2025).
tumor (continued). "A subset of mutated Lgr5+ stem cells may become cancer stem cells (CSCs), which drive tumor initiation and growth due to their self-renewal and differentiation abilities." (PMID 39456736, 2024). "Interestingly, the cell clusters associated with HCC tumours consistently expressed 3–5-fold lower levels of LGR5 relative to adjacent cells." (PMID 39169164, 2024). "LGR5-positive SC has been implicated in both normal GI homeostasis and tumor development." (PMID 37686516, 2023). "In conclusion, we suggest that co‐implantation of LGR5+ tumor cells with cancer‐associated fibroblasts could increase tumor size and promote further metastasis." (PMID 37578396, 2023). "Moreover, the intrinsic plasticity of LGR5− enterocytes to revert to LGR5+ cells and then re-establish the cellular hierarchy upon loss or ablation of LGR5 further implicates LGR5 in both tumor initiation and metastatic outgrowth." (PMID 36833408, 2023). "Moreover, a loss of LGR5 was observed, which was demonstrated by Emery, who showed the ability of tumor cells switching between expressing LGR5 in normoxia and repression in hypoxic conditions." (PMID 36681673, 2023). "However, after several weeks, tumor regrowth is observed and associated with differentiated tumor cells that dynamically replenish the pool of LGR5+ CCSCs, indicative of cellular plasticity." (PMID 33806312, 2021). "Notably, an increased level of the tumor suppressor, miR-142-3p, whose targets include LGR5, IL-6, and ABCG2, was detected in association with MSI-N1014 treatment." (PMID 32560222, 2020). "Interestingly, a cross-talk between TGF-β signaling and the R-spondin/LGR5 axis was reported in CRC cells, where LGR5-induced TGF-ß activity in tumor cells was associated with a decreased tumor invasion and metastasis." (PMID 33260962, 2020). "This review is to summarize our current knowledge about the importance of Lgr5 in cancer biology and the underlying molecular mechanisms of Lgr5-mediated tumor-promoting/suppressive activities, as well as potentially useful preventive strategies in treating tumor." (PMID 31358061, 2019). "The expression of E2A was inversely associated with Lgr5 expression (P < 0.05), which indicates that E2A expression may correlate with tumor-initiating capacity of CRC cells." (PMID 31234887, 2019). "Similarly, combination of MUN or PhIP treatment with PP2A deficiency in Lgr5+ cells also induced tumor formation in vivo." (PMID 31905853, 2019). "Furthermore, our results of univariate analysis indicated that TNM stage (Tis+I+II vs. III), Lgr5 expression (low vs. high), and number of tumor infiltrating Tregs (low vs. high) were associated with OS in GC patients." (PMID 31417548, 2019). "We investigated whether tumorigenesis generated by DMBA treatment and PP2A deficiency in mouse Lgr5+ cells reflects tumor formation in vivo." (PMID 31905853, 2019). "Furthermore, this result suggests that an increase in Lgr5 expression is associated with a tumor-suppressive immune microenvironment in GC patients." (PMID 31417548, 2019). "We then determined whether LGR5 expression was associated with clinicopathological tumor features, including age, tumor grade, tumor size, lymph node (LN) status, ER status, PR status, and HER2 status." (PMID 29471794, 2018). "In the present study, our data showed that Lgr5 expression was significantly associated with the depth of tumor invasion, lymph node metastasis, and perineural invasion, parallel to those reported previously in the Chinese CRC patients and also in the Japanese patients." (PMID 30046385, 2018). "Moreover, up-regulated LGR5 was associated with larger tumor diameter (>5cm, P=0.001), higher TNM stage (P=0.021), increased recurrence (P=0.023) and growing metastasis (P=0.030)." (PMID 28881613, 2017).
tumor (continued). "LGR5 was found to be overexpressed in several solid malignant tumors, having a close association with initiation and recurrence of different cancer types and correlating with tumor growth, invasion, and poor outcome." (PMID 29215551, 2017). "Notably, we also observed increased tumour formation initiated directly from LGR5‐positive stem cells in Huwe1‐deficient intestines." (PMID 28003334, 2017). "In a separate cohort of 33 human patients with known BRAFV600E mutational status, LGR5 positivity was strongly associated with BRAFV600E mutational positivity by protein analysis (p = 0.005), strengthening the conclusion that LGR5 tumor positivity is associated with markers of tumor aggressiveness." (PMID 26416247, 2015). "Moreover, lgr5 methylation is also reversely associated with high tumor grade and positive distant metastasis." (PMID 26599100, 2015). "Multivariate Cox's regression hazard analysis revealed an increased risk (RR = 1.8, P = 0.12) of tumor-related death for patients with a low wild type LGR5/GPR49 mRNA level and a 2.6-fold (P = 0.026) increased risk for STS patients with a low level of GPR49Δ5 mRNA in their tumors, respectively." (PMID 21978106, 2011). "Furthermore, specific loss of Apc in LGR5-positive cells results in progressively growing neoplasias." (PMID 20386750, 2010). "LGR5 was recently shown to be a stem cell marker of cells of the small intestine and colon and stem-cell specific loss of Apc results in progressively growing neoplasias." (PMID 20386750, 2010). "Key to solving this conundrum will be to stratify poorly differentiated tumours, according to whether they cluster with Lgr5+EPHB2+ ISCs or display methylation of CSC-associated Wnt-target genes, to identify patients that may benefit from Wnt antagonists or agonists, respectively." (PMID 33673710, 2021). "Besides, in vivo experiments revealed that only coculture with Lgr5 cells or the supernatant from Lgr5 cells that both isolated from Gprc5a-deficient mice could lead to tumor formation." (PMID 32157214, 2020). "Despite the clear evidence showing the Lgr5‐dependent role in the siRNA assay and the enhanced sensitive to RSPO stimulation in vivo, it is admittedly difficult to dissect whether the enhanced stem cell and tumour phenotypes in the mutant intestine are caused by Lgr5 or Dvl2 or both." (PMID 31867777, 2020). "Furthermore, LGR5 was found to be overexpressed in several carcinomas having a close association with initiation and recurrence of different cancer types and correlating with tumor growth, invasion and poor prognosis." (PMID 30770730, 2019). "However, tumor-initiating mutations can occur in Lgr5+ crypt stem cells and in differentiated Lgr5− cells, indicating that the two hypotheses are not mutually exclusive." (PMID 31905853, 2019). "In addition, drug screening targeting Lgr5-associated signaling pathways in tumor organoids ex vivo might provide a powerful tool for the development of novel drugs for personalized anti-tumor therapy." (PMID 31358061, 2019). "The resulting Lgr5+ hepatocyte-derived BrafV600E-driven tumours expressed the zone 1 marker CDH1 and had reduced expression of the zone 3 and WNT marker GLUL." (PMID 41261129, 2026). "Whilst LGR5 + ISC expansion is a critical step for tumour initiation and progression, its regulation is poorly understood." (PMID 41856980, 2026). "Intriguingly, we found that RSPO4 suppressed Wnt/β-catenin signaling in both LGR4 and LGR5 expressing tumor cells." (PMID 41522353, 2026). "Several high-scoring proteins, including ITGB8, LGR5, FZD7, HLA-E, ANGPTL2, and BST2 emerged as candidates potentially affected by protonation-linked perturbations in acidic tumor microenvironments." (PMID 42036641, 2026). "LGR5, a receptor involved in the Wnt signaling pathway, is associated with CSC maintenance and aggressive tumor behavior is linked to tumorigenic potential and poor prognosis in cancers." (PMID 41438576, 2026).
tumor (continued). "By sphere formation assay, we found that FUm1/2 mutant expression lost the inhibitory effect of RSPO4 on cancer cell stemness of both LGR4+/LGR5- and LGR4-/LGR5+ tumor cells." (PMID 41522353, 2026). "A humanized monoclonal LGR5 antibody - BNC101 targeting LGR5 in tumor biopsies was evaluated in safety and dose escalation phase I clinical trials in patients with recurrent metastatic CRC." (PMID 39821694, 2025). "Overall, α-LGR5 CAR T cells demonstrated strong efficacy in killing LGR5-expressing tumour cells in vitro and promising activity against pre-B-ALL tumours in vivo." (PMID 40405910, 2025). "LGR5 expression also marks tumour-initiating cells (TICs) in intestinal epithelial tumour cells, forecasting similar expression in other tumour types including human TICs." (PMID 40405910, 2025). "At the same time, bispecific engagers can rapidly recruit T cells to kill LGR5-expressing tumour cells, providing an off-the-shelf therapeutic with flexible dosing options." (PMID 40405910, 2025). "During CRC progression, colonic LGR5+ SCs undergo profound changes that underpin tumor growth, heterogeneity, and metastatic potential." (PMID 41002393, 2025). "Emerging evidence suggests a potential tumor‐suppressive role of LGR5, possibly through its capacity to constrain cell proliferation." (PMID 40661135, 2025). "Compact tumor organoids exhibited a higher expression of genes involved in WNT-mediated maintenance of nephron progenitors (e.g. LGR5, MYCN, HMGA2, LIN28B, NCAM, WNT4, BMP7)." (PMID 39740515, 2025). "Apc knockout is necessary in LGR5+ cells in the intestinal crypt for tumour formation and few effects are seen with knockout in committed lineages higher up in the villus or in the transit‐amplifying zone, where microadenomas rapidly stall." (PMID 40212011, 2025). "Further studies are warranted to address the discrepancies in the role of LGR5 in cancer migration and tumor invasion." (PMID 39821694, 2025). "Among the top 100 deregulated genes, Wnt-associated genes such as LGR5, DKK1, and NKD1, as well as the HB-related genes DUSP9, DLK1, PEG3, PEG10, IGF2BP1, and IGF2BP2 were consistently upregulated in tumor samples." (PMID 40968384, 2025). "Another in vivo CRC study selectively depleted the LGR5 + stem cell population also showed that LGR5- cells drive tumor metastasis and migration." (PMID 39821694, 2025). "Although the majority of cancer studies suggest that LGR5 promotes tumor growth, several studies have reported the opposite results." (PMID 39821694, 2025). "Downstream of β-catenin, target genes such as TCF1, Cyclin D1, Axin2, Lgr5, and c-Myc promote cell cycle progression in both tumor cells and SSCs." (PMID 40638605, 2025). "Increasing evidence suggests that endogenous LGR5-positive cell population contributes to tumor initiation, progression, and metastasis." (PMID 41194856, 2025). "Preclinical studies, including antibody-based and CAR-T approaches, have shown promising antitumor activity against LGR5-positive cells, though challenges such as tumor heterogeneity and potential toxicity to normal stem cells remain." (PMID 41194856, 2025). "The LGR5+ stem‐like cell signature exhibited significant associations with MSI status, POLE mutations, and tumor staging." (PMID 40661135, 2025). "If WNT is activated directly, the stem cell compartment is expanded, with tumours more likely to initiate from LGR5+ cells." (PMID 40212011, 2025). "LGR5 was identified as a target for the treatment of NB thanks to its high expression in NB cell lines, as well as in primary tumor samples from NB patients." (PMID 40129921, 2025). "The epithelial cells were grouped into categories including goblet cells, transit amplifying cells, mature basal cells, LGR5+ stem cells, RSCs, and tumor cells." (PMID 39656543, 2025).